SNORA11F (small nucleolar RNA, H/ACA box 11F)
Gene: Small nucleolar RNA gene on chromosome 10 (73,126,080 to 73,126,207, reverse strand). Ensembl gene ENSG00000221164.
Gene Ontology:
Biological process: RNA processing
Cellular component: nucleolus
Homologues: Orthologues: chimpanzee SNORA11F (99% identical), macaque SNORA11F (98% identical). Paralogues in human: SNORA11D (94% identical), SNORA11E (94% identical), SNORA11B (89% identical), SNORA11C (88% identical), SNORA11 (85% identical), SNORA11G (76% identical).